INS (insulin)
Diseases named in the same sentence as INS in open-access papers (continued):
Sharing a sentence is not in itself a finding about the gene and the disease.
Obesity (continued). "However, independent of obesity, overnutrition can directly blunt central insulin sensitivity, even before peripheral insulin signaling is impaired." (PMID 35873818, 2022). "Interestingly, the absence of both JNK1 and IKKβ pathways results in improved insulin sensitivity and enhanced insulin receptor signaling in mouse models of obesity." (PMID 35327570, 2022). "Furthermore, effects of IN insulin on fMRI signals elicited by food stimuli are weaker or absent in individuals with type 2 diabetes or obesity." (PMID 35397638, 2022). "We aimed to determine whether pancreatic fat negatively affects β-cell function and insulin secretion in women with overweight or obesity but without T2DM." (PMID 36584200, 2022). "Therefore, reduced inflammation, increased insulin sensitivity, up-regulated BDNF, and suppressed apoptosis of neurons may be the critical molecular mechanisms for ameliorating obesity-induced cognitive decline during the process of body weight loss." (PMID 35745162, 2022). "Indeed, it has been hypothesized that the dysregulation of insulin signaling as observed in T2DM, metabolic syndrome, and obesity also extends to the brain in so-called “insulinopathies of the brain”." (PMID 36028833, 2022). "It is noteworthy that elevated insulin levels were more common in patients with stable plaques and without obesity, which may indicate that in conditions of insulin sensitivity, its potentially protective properties are revealed." (PMID 36013196, 2022). "Phenotypically, cluster 4 individuals with obesity also exhibited consistently higher serum insulin levels; and while not different in height, BMI or relative fat mass (fat mass index; FatMI), cluster 4 individuals with obesity showed increased relative lean mass (lean mass index; LeanMI)." (PMID 36097183, 2022). "Indeed, its function relies on increasing insulin-mediated glucose uptake by activating the protein kinase B (PKB or Akt) pathway, and decreased serum concentrations have been detected in individuals with obesity and T2DM." (PMID 35206286, 2022). "Furthermore, in vivo models of mouse obesity have demonstrated that the absence of JNK1 would improve insulin sensitivity." (PMID 35712257, 2022). "Additionally, fructose intake which is associated with the pathogenesis of metabolic diseases such as non-alcoholic fatty liver disease (NAFLD), obesity, hyperuricemia and hypertension, seems not to stimulate insulin secretion." (PMID 36185667, 2022). "However, no obvious difference was found in hypertension and obesity prevalence, smoking status, alcohol intake, metformin and insulin sensitizers use, WHR, SBP, DBP, and glycated hemoglobin A1c (HbA1C) among the serum iron quartile groups." (PMID 36133303, 2022). "Overall, offspring born to women with GDM had higher BMI z-score, higher systolic blood pressure and diastolic blood pressure, higher childhood overweight and obesity rates, higher lipid profile levels, and higher insulin and insulin resistance levels, than those born to women without GDM." (PMID 35784581, 2022). "The impact of these predictive values could not be explained by body mass, which demonstrates that insulin sensitivity, but not necessarily obesity, is predictive for future weight management." (PMID 36170006, 2022). "Nerveless insulin secreted by pancreatic β-cells and transported by cerebrospinal fluid (CSF) can cross the BBB via a saturable receptor-mediated transport, whose efficiency can decrease by pathological conditions, such as obesity, inflammation, and Alzheimer’s disease." (PMID 35741464, 2022). "Indeed, administration of IL-1RA improves insulin sensitivity in animal models of obesity, suggesting IL-1RA-dependent homeostatic regulation of IL-1 signaling is not fully functional in obesity." (PMID 36938490, 2022).
Obesity (continued). "Unlike the conventional Ido−/− mice, the Ido1-lKO mice following a 12-week of HFD induction exhibited comparative bodyweight change and insulin sensitivity as their littermates, confirming that macrophages are not the critical target for IDO1 modulation of the development of obesity." (PMID 35715443, 2022). "As reflected in our results in mice, it remains a possibility that the current diet may have a significant impact on insulin sensitivity irrespective of the obesity status of an individual." (PMID 36394259, 2022). "However, the extent of this may be related to confounding variables, such as obesity or common biological pathways, such as IGF signaling, dysregulation of ovarian steroid hormones and increased insulin levels." (PMID 35207688, 2022). "Knowing the action of insulin and that the mainstay of treatment for obesity are diet and exercise, one of the necessary approaches is developing treatment strategies with lowest possible daily insulin dose that would at the same not impair the glycemic control." (PMID 36303875, 2022). "Given that protection from HFD-induced glucose intolerance in βKO mice occurred without changes in obesity and stemmed from a genetic change restricted to beta-cells, we expected that higher plasma insulin concentrations would explain the decrease in hyperglycemia." (PMID 34823065, 2022). "Diet-induced obesity in mice altered brain insulin gene expression, in a neuroanatomically divergent manner; while in the hypothalamus the expected obesity-induced reduction was found, in the DVC diet-induced obesity resulted in increased expression of the insulin gene." (PMID 36244663, 2022). "Moreover, it would be of great interest to investigate the impact of RF on insulin sensitivity and glycemic variability throughout the day in individuals with overweight or obesity and/or without glucose abnormalities." (PMID 36432465, 2022). "The beneficial effects of postbiotics have been observed on body weight, insulin sensitivity, and glucose balance; SCFA can also improve the intestinal barrier, reduce inflammation, positively affect lipid metabolism, and protect against obesity through a high-calorie diet." (PMID 35806234, 2022). "In addition, many hormones and cytokines altered with obesity may influence ADPKD progression, including increased levels of insulin, insulin-like growth factor 1 (IGF-1), leptin, TNF-α, and IL-6, as well as decreased adiponectin." (PMID 35350649, 2022). "Hyperglycemia in the absence of obesity probably means diminished insulin secretion." (PMID 35010830, 2022). "Also, the A/L ratio was shown to be a stronger correlate to IR than adiponectin or leptin alone, an independent predictor of insulin sensitivity (IS) in women with moderate obesity and men presenting obesity without or with MetS, glucose intolerance or T2D." (PMID 35436409, 2022). "There is critical need for more studies describing intracellular signaling, transcription/translation, insulin/IGF-1 signaling, as well as the roles of plasma and muscle lipids, and amino acid delivery/blood flow in regulating protein synthesis and breakdown in muscle of humans with obesity." (PMID 35350688, 2022). "However, these diurnal patterns may be altered in adults with obesity and/or T2DM with the greatest insulin sensitivity at around 07:00 and the lowest in the morning." (PMID 36432465, 2022). "Furthermore, obesity-related inflammation leads to the upregulation of SOCS3 proteins in several tissues, leading to the inhibition of insulin signaling and, therefore, representing an interesting mechanism connecting the immune and metabolic system in a delicate and balanced cross-talk." (PMID 35631263, 2022). "In metabolically unhealthy subjects with obesity, a one-year program combining Mediterranean diet nutritional counselling and high-intensity interval training (HIIT) improved the body composition, fasting glycaemia, insulin sensitivity, VO2 peak, and muscle endurance." (PMID 36145083, 2022).
Obesity (continued). "The mechanism linking BMI and ATN is not too clear, however, it is suggested that obesity and insulin resistance increase thyroid stimulating hormone secretion via leptin signaling, ultimately resulting in the expansion of thyroid volume and formation of nodules." (PMID 35108333, 2022). "In addition to increased IL8 production from insulin resistant muscle itself, the high levels of IL8 released from IMAT in obesity may result in elevated local levels of IL8, which is associated with reduced substrate delivery, in addition to inflammation." (PMID 35980018, 2022). "Indeed, we found that performing physical activity affects metabolic parameters in youths with obesity, restoring normal values of HOMA-IR index and fasting insulin, as well as reducing the amount of circulating EVs to a level comparable to normal weight controls." (PMID 36613885, 2022). "Therefore, the primary objective was to investigate changes in insulin sensitivity and substrate oxidation at rest and during submaximal exercise in individuals living with or without obesity following a 4‐week SIT intervention." (PMID 34110721, 2021). "In obesity, the imbalance of endocannabinoid peripheral signaling also depends on a reduction in FAAH metabolites, which impacts visceral fat, leading to CB1R overstimulation and subsequent adiponectin inhibition, resulting in the exacerbation of insulin resistance and low-grade inflammation." (PMID 34073983, 2021). "In addition, pattern recognition receptors (PRRs) activate the inflammation status and the presence of nutritional free fatty acids (FFAs), which display a negative impact on insulin target tissues in obesity." (PMID 33802371, 2021). "Enhancement of insulin signaling, together with inhibition of JNK activation and of the production of proinflammatory cytokines by BAT, may be involved in the ability of exercise to alleviate obesity." (PMID 34082784, 2021). "Carbohydrate-restricted diets have been used effectively to treat obesity and T2DM for over 100 years, and their effectiveness may simply be due to lowering the dietary contribution to glucose and insulin levels, which then leads to improvements in hyperglycemia and hyperinsulinemia." (PMID 34447776, 2021). "Moreover, IN oxytocin administration prior to an oral glucose tolerance test resulted in increased insulin secretion and improved beta cell responsivity in lean men, but not in men with class II obesity (BMI 35.3 ± 1.12 kg/m2)." (PMID 34299356, 2021). "Furthermore, insulin almost fully suppressed circulating fatty acid levels in all conditions, suggesting that the maximum action of insulin on fatty acid handling is not influenced by obesity." (PMID 34321614, 2021). "Obesity, clinically evident as hyperglycemia or high blood glucose is known to increase the expression of miR-212-3p, possibly via calmodulin binding transcription activators CAMTA1 and 2 and its target genes, collectively increasing insulin secretion from beta cells in the pancreatic islets." (PMID 34827683, 2021). "In addition, these offspring have increased insulin secretion in utero, which correlates with impaired glucose tolerance in childhood independent of obesity in the offspring." (PMID 34155315, 2021). "Given these connections between mitochondrial morphology, adipokines, obesity, and cancer, it will be important to assess the effects of SH‐BC‐893 on mitochondria in tumors and its effectiveness in tumor models that are sensitive to a HFD and/or leptin and insulin levels." (PMID 34231322, 2021). "Therefore, the aim of this study was to assess serum SFRP5 concentration in a young healthy population in relation to insulin sensitivity and obesity and its regulation by hyperinsulinemia and/or serum free fatty acids (FFA) elevation to evaluate the link between SFRP5 and insulin sensitivity." (PMID 34184187, 2021). "Thus, SIT impacts fat oxidation during exercise in individuals living with obesity while having no such influence on insulin sensitivity." (PMID 34110721, 2021).
Obesity (continued). "Therefore, our study objective is to identify the association between insulin treatment in pregnancy and the risk of postpartum psychological distress (abbreviated here as PPD) among cohorts of women with and without obesity." (PMID 33743677, 2021). "Interestingly, the role of PVAT has been connected with vascular pathologies, mostly in the context of obesity, fat overload and insulin resistance, but not with early hyperglycemia or specific alterations in insulin signaling." (PMID 34207844, 2021). "Interestingly, when we analyzed insulin signaling through Akt phosphorylation, we observed that PIO treatment was not able to reverse insulin signaling in the artery of mice with obesity, even though it clearly improved whole-body insulin sensitivity." (PMID 34552556, 2021). "Because obesity is one of the main driving factors of NAFLD, in the study of probiotics to improve NAFLD, it is necessary to specifically evaluate the changes of body fat rate, TG, insulin sensitivity, fat inflammation, and various metabolic parameters to determine its function." (PMID 34393826, 2021). "The CR mimetic action of BBR has been established by numerous studies performed using in vitro and in vivo models of obesity or diabetes or cardiovascular pathological conditions: BBR, activating mainly AMPK, reduces body weight and hepatic lipid accumulation, and it also improves insulin action." (PMID 34360538, 2021). "Third, because we used secondary data from KNHANES, we could not evaluate the levels of obesity-related hormones, such as insulin, estrogens, androgens, growth hormone, and leptin, which regulate adipose tissue distribution, metabolism, and appetite." (PMID 34836286, 2021). "Thus, obesity is neither sufficient nor sensitive for predicting who will become insulin resistant and metabolically unhealthy, and who will develop T2D." (PMID 34277974, 2021). "Interestingly, severe CIH plus obesity did not change any of these metabolic parameters, since fasting glucose and insulin levels, as wells as insulin resistance were not modified when the HF animals were exposed during 14 days to severe CIH." (PMID 34439481, 2021). "Abdominal adiposity and obesity could contribute to ovarian hyperandrogenism and adrenal also through mechanisms independent of insulin resistance." (PMID 34886216, 2021). "Obesity is a very complex abnormal state, accompanied by various physiological and molecular alterations, which involves the complicated roles of adipokines (leptin, adiponectin, resistin, visfatin, and SFRP5), insulin, IGF, sex hormone, and chronic inflammation." (PMID 34350120, 2021). "However, the sex-specific impact of maternal obesity exposure on insulin secretion in human offspring has not been studied extensively." (PMID 34108935, 2021). "Activation of PPAR-δ by FA components of a high-fat diet, hormonal imbalance related to obesity including insulin/IGF-1 resistance and adiponectin decline, increase in inflammation, and metabolic alteration by high-fat diet-induced obesity and microbiota dysbiosis could be named." (PMID 33827616, 2021). "In addition, when fed a high‐fat diet, mice lacking α‐CGRP have improved insulin sensitivity and glucose handling compared with wild‐type mice, including protection against diet‐induced obesity." (PMID 33855218, 2021). "Interestingly, insulin levels were higher in normal-weight PLWH cases than in the overweight/obesity uninfected group (7.9 vs 6.5), although not statistically significant." (PMID 34019585, 2021). "Under obesity conditions, the accumulated lipids in skeletal muscle cells promotes muscle cells to obtain energy through lipid oxidation, resulting in the production of 4-hydroxy-2-hexenal (4-HHE), a lipid aldehyde that affects insulin-induced IRS1/IRS2 phosphorylation." (PMID 34948944, 2021).
Obesity (continued). "Moreover, obesity is a prevalent manifestation of metabolic disorders, and accumulating evidence has demonstrated that TC, TG, LDL-C, INS, and LEP levels were significantly higher in obese than in normal weight people, while the concentrations of ADP and ghrelin decreased." (PMID 33585429, 2021). "Subsequently, a second search topic with the following keywords was performed: (obesity AND adults AND exercise AND anaerobic threshold AND physical training) AND growth hormone OR GH OR non-esterified fatty acids OR NEFA OR insulin resistance OR lactic acid OR leptin OR body composition." (PMID 34047810, 2021). "A previous study examined IR using HOMA-IR suggested that the obesity paradox for mortality exists in insulin-resistant patients but not insulin-sensitive patients, suggesting IR may be part of the underlying mechanism of the obesity-stroke paradox." (PMID 33967936, 2021). "Additionally, individuals without obesity had an increase in insulin AUC, while glucose AUC did not significantly change from baseline." (PMID 34110721, 2021). "Interestingly, although participants living with obesity were normoglycemic, a significant decrease in the AUC for glucose was observed whereas no change was observed in the AUC for insulin." (PMID 34110721, 2021). "Notably, we recently showed an improvement of systemic oxidative stress in response to exercise training in black African women with obesity, but this was not correlated with the reported improvement in insulin sensitivity." (PMID 33921645, 2021). "In addition, in obesity, flavonoids exert beneficial effects related to the insulin signaling on non-classical insulin-targeted tissues, such as the endothelium and brain." (PMID 34208379, 2021). "We think low insulin reserves in the pancreas and resulting poor blood glucose control disrupts adipose tissue functions creating a negative effect on endotrophin levels, together with obesity." (PMID 33478575, 2021). "However, subjects with the MHOW/O phenotype displayed higher values for all indices of obesity measurement, had higher lipid parameter values and were more insulin-resistant than the healthy non-obese individuals (MHNW)." (PMID 34616552, 2021). "Based on data collected in a review by Kane and Sinclair, sirtuins appear to have a protective effect on obesity, although their effects are complex and may either be related or independent of insulin action and glucose regulation." (PMID 33435147, 2021). "Given the insulin secretion stimulatory effect of BCAAs on β-cells, the high levels of BCAAs observed in obesity and T2DM may suggest a deleterious long-term effect or resistance to their function similar to what happens to FGF-21 in obesity." (PMID 33672162, 2021). "Here, we show that feeding in the late active phase (the Evening group) might induce insulin resistance in the whole body and skeletal muscles without hyperphagia and obesity." (PMID 34639172, 2021). "While the direct comparison between women with obesity treated with insulin and those without insulin treatment did not attain significance, mothers with obesity who received insulin in pregnancy have similar rates of PPD to lean mothers who did not receive insulin." (PMID 33743677, 2021). "As a result, the (supposedly negative) effect of insulin on Glu may be offset by a positive effect of obesity." (PMID 33509165, 2021). "Obesity was associated with low plasma ANGPTL8 concentrations (normal weight 32.45 ± 5.57 vs. obesity 19.69 ± 1.49 ng/mL, p = 0.004), regardless of the degree of insulin resistance." (PMID 34884755, 2021). "A recent review has identified that myostatin may play an important role in contributing to the negative cycle of obesity by not only adversely regulating muscle mass but also reducing lipid oxidation and insulin sensitivity." (PMID 33801275, 2021). "Mice lacking PTP1B are hypersensitive to leptin resistance, obesity, and insulin level." (PMID 33273564, 2020).